IL4 (interleukin 4)
Diseases named in the same sentence as IL4 in open-access papers (continued):
Sharing a sentence is not in itself a finding about the gene and the disease.
COVID-19 (continued). "In addition, IL-1β, IL-4, IL-6, IL-18, IL-35, PGE2, and TXA2 levels in moderate and severe COVID-19 patients were significantly higher (p < 0.001) than in healthy controls." (PMID 36298501, 2022). "In addition, Tim-3+ NKT cells in COVID-19 presented a stronger capacity to secrete IFN-γ, IL-4 and IL-10 compared with healthy individuals, they also demonstrated high expression of co-inhibitory receptors such as PD-1, CTLA-4, and LAG-3." (PMID 35250975, 2022). "The cytokine storm has already been attenuated following recovery from COVID-19, as levels of TNF-α, free active TGF-β, IFN-γ, IL-1β, IL-2, IL-4, IL-6, IL-8, IL-10, IL-12p70, IL-17 and MCP-1/CCL2 during convalescence were not higher compared to healthy volunteers." (PMID 35757700, 2022). "Our results indicate a similar proinflammatory profile in COVID-19+ patients with or without pregnancy and probably regulated at least partially by IL-4 in pregnant women." (PMID 35901034, 2022). "Therefore, we analyzed the viral loads and the differential gene expression profiles of eight cytokines (IL-1, IL-2, IL-4, IL-6, IL-10 IFN-γ, TNF-α, and TGF-β1) in a total of 118 qPCR confirmed COVID-19 cases." (PMID 36584119, 2022). "The increased production of IL-10, but not of IL-4, in severe COVID-19 suggests that IL-10 is the main cytokine that counteracts the inflammatory response cascade triggered by the Th1 type response." (PMID 36287506, 2022). "In addition, patients with COVID-19 had higher IFN-γ, IL-4, IL-5, and IL-6 concentrations compared to patients with influenza and higher IFN-γ and IL-10 concentrations compared to patients with bacterial CAP." (PMID 34987205, 2022). "Of note, flow cytometric analysis of unstimulated whole-blood samples revealed no significant enrichment in the percentage of IL-4+ or IL-17A+ lymphoid cell populations in COVID-19 patients relative to HVs." (PMID 33232303, 2021). "To investigate the role of cytokines and chemokines in the inflammatory status of COVID-19 and MIS-C, we measured plasma levels of IL-1ß, IL-2, IL-4, IL-5, IL-6, IL-10, TNF-α, IL-17A, IFN-α, IFN-γ, CXCL10/IP-10, CXCL8/IL-8, CXCL9/MIG, CCL5/RANTES, and CCL2/MCP1." (PMID 33841438, 2021). "In the nonsevere COVID-19 group, the correlation coefficients of IL-4 and IL-2, TNF-α and IL-2, TNF-α and IFN-γ, and TNF-α and IL-4 were 0.887, 0.795, 0.699, and 0.674, respectively." (PMID 34712741, 2021). "Additionally, there were higher correlations between IL-2 and IL-4, TNF-α and IL-2, TNF-α and IL-4, TNF-α and IFN-γ, and CD16+CD56+NK cells and various subsets of T cells in COVID-19 patients." (PMID 34712741, 2021). "Here, we also observed interstitial inflammation and expression of IL-4 in the lungs of COVID-19 patients but not pandemic influenza A(H1N1) subjects." (PMID 33995342, 2021). "A recent proteomic profiling study pointed to DC-SIGN as a mediator of genetic risk in COVID-19 and finally DC/L-SIGN expression is induced by proinflammatory cytokines such as IL-4, IL-6, IL-10 and IL-13, known to be overexpressed in severe SARS and COVID-19 cases." (PMID 34015061, 2021). "For example, IL-4 and IL-5 levels were not increased in wave 2 COVID-19 patients, suggesting lack of type 2 immunity activation." (PMID 34675240, 2021). "Monocytes were negatively correlated with IL-2, IL-4, and TNF-α in the COVID-19 severe group." (PMID 34712741, 2021). "The COVID-19 samples presented statistically increased tissue immunoexpression of ACE-2 (p < 0.0001), AKT-1 (p = 0.022), CD44v6 (p < 0.0001), IL-4 (p < 0.0001), MMP-9 (p = 0.004), α-SMA (p < 0.0001), Sphingosine-1 (p < 0.0001), and TGF-β1 (p = 0.0315) when compared to the CONTROL group." (PMID 35008594, 2021). "We have found fifteen cytokines that remain upregulated in convalescent COVID-19 individuals one month after infection (IL-1α, IL-3, IL-10, IL-12p70, CCL7, IFN-α2, bFGF, LIF, TRAIL, IL-2, IL-4, IL-5, IL-12p40, IL-17 and MIF) indicating a strong activation of the immune response." (PMID 34681885, 2021).
COVID-19 (continued). "It suggested that the presence of HLA-DQ2 in 90% of CD subjects reduced T-helper interactions, down-regulated cytokine production such as IL-4 and IFN γ, and may alleviate COVID-19 symptoms among CD or RCD cases." (PMID 35154599, 2021). "In addition, symptomatic COVID-19 mothers had statistically significant elevated levels of 4 of the 10 inflammatory markers (IFN-γ, IL-4, IL-6, and IL-12) compared to asymptomatic COVID-19 mothers." (PMID 34382820, 2021). "Clinical studies show that the levels of IL-2, TNF-α, IFN-γ, IP-10, MCP-1and other pro-inflammatory cytokines are significantly increased in severe or critical patients with COVID-19, while SARS-CoV-2 infection also increases secretion of anti-inflammatory cytokines (IL4 and IL10)." (PMID 32665783, 2020). "Cytokines related tissue repair, such as IL-10, IL-4, and IL-5, were also upregulated in COVID-19 patients, but without statistical significance between mild and severe patients." (PMID 32641700, 2020). "TNF-α, IFN-γ, and IL-2 were also higher while IL-4 was lower in severe COVID-19 cases than in mild cases, but the difference was not significant." (PMID 32669467, 2020). "The expression levels of a 13-cytokine panel (IL-1α, IL-1β, IL-2, IL-4, IL-5, IL-6, IL-8, IL-10, IL-12, NF-κβ, and IFN-α, IFN-β, and IFN-γ) were measured by qRT-PCR from peripheral blood mononuclear cells (PBMC) obtained from the patient with TEN and their parents (which were positive for COVID-19)." (PMID 39941142, 2025). "In our study, we found that the interleukins primarily involved in TEN were IL-4, IL-6, and IL-12, which were modulated (downregulated) by TEN, along with augmented IL-1α, IL-1β, IL-5, IL-8, NF-κβ, and interferons (IFN; α, β, and γ), which were modulated by COVID-19." (PMID 39941142, 2025). "One of the objectives of our study was to molecularly and biologically evaluate the levels of pro-inflammatory cytokines (IL-1, IL-6) and anti-inflammatory cytokines (IL-4, IL-10) in the appendixes of children with COVID-19, considering the lack of data on this in the global literature." (PMID 38397914, 2024). "In this regard, it has been reported that post-COVID-19 patients develop a cytokine syndrome characterized by an imbalance of pro-inflammatory and anti-inflammatory cytokines, such as IL-17 and IL-2, and IL-10 and IL-4, compared with COVID-19 patients without sequelae." (PMID 36836568, 2023). "However, the results of that study showed that IL-2 and IL-4 are not significantly altered in severe and nonsevere COVID-19 patients." (PMID 37649897, 2023). "Thus, we speculate that the persistent high levels of IL-4 reported during SARS-CoV-2 infection and in the post-acute phase are responsible for the downregulation of the 5-LOX protein in COVID-19 and long-COVID patients, compared with healthy donors." (PMID 36613462, 2022). "Across all the soluble proinflammatory markers we examined, ICAM, IL-1β, IL-4, IL-6, TNFα, and Syndecan showed a statistically significant positive correlation between cytokine or epithelial marker and antibody quantity regardless of COVID-19 disease severity." (PMID 36865568, 2022). "In addition, there were higher correlations between IL-2 and IL-4, TNF-α and IL-2, TNF-α and IL-4, TNF-α and IFN-γ, and NK cells and T cells in COVID-19 patients, and there was a higher correlation between CD3+CD4+ T cells and CD19 + T cells in cancer patients." (PMID 34712741, 2021). "Moreover, the serum levels of IFN-γ, TNF-α, IL-2, IL-4 and IL-10 were not correlated with disease severity among COVID-19 patients." (PMID 34123873, 2021). "A significant increasing trend of IL-1β, IL-1ra, IL-2, IL-4, IL-5, IL-6, IL-7, IL-8, IL-10, IL-12(p70), IL-15, IL-17, FGF-b, G-CSF, GM-CSF, IFN-γ, IP-10, MCP-1, MIP-1α, PDGF, TNF-α, and VEGF was observed in the three groups (Controls ≤ Mild COVID-19 ≤ Severe COVID-19)." (PMID 34675240, 2021).
COVID-19 (continued). "However, another study which included 25 confirmed COVID-19 patients who were admitted to ICU showed that circulating levels of IL-2, interleukin-4 (IL-4), tumor necrosis factor-α (TNF-α), interferon (IFN-γ) and CRP were not directly correlated with symptom severity of COVID-19." (PMID 34282057, 2021). "Some type 2 cytokines (IL-4, IL-9, IL-13, etc.)have inhibitory effects on the production of proinflammatory cytokines (IL-1β, IL-6, TNF-α, etc.), the overactivation of which have been proposed as a potential key mechanism of protection against COVID-19 to some extent." (PMID 35082829, 2021). "Furthermore, unlike SARS patients, patients with COVID-19 also have elevated levels of Th2 cell-secreted cytokines (such as IL-4 and IL-10), which inhibit the inflammatory Th1 responses." (PMID 33324414, 2020). "Specifically, we compared the levels of IFN-γ, IL-6, IL-22, IL-4, IL-8, IL-10, and IL-17A between anti-SARS-CoV-2 IgG-positive and seronegative individuals, all without a history of COVID-19." (PMID 40160814, 2025). "PLWH with COVID-19 with an undetectable VL had higher concentrations of IL-2, IL-4, and IFN-γ than PLWH without COVID-19 with a detectable VL." (PMID 39597537, 2024). "More than 98% of the HCWs with severe COVID-19 had cytokine levels (IFN-γ, IL-10, IL-2 and IL-4) in the normal ranges." (PMID 36908474, 2023). "Moreover, the IL-15 immunotherapy may be a feasible strategy for COVID-19, as it induces innate immune responses via the induction of NK cells, CD8+ T cells, and T regulatory cells to neutralize Th2 cytokine storms, leading to decreased levels of IL-4, IL-5, and IL-13." (PMID 35679246, 2022). "Our results show a significant increase in serum IL-4 levels in COVID-19 ICU patients; this suggests that the source of IL-4 is not neutrophils and proposes an immunomodulatory effect on IL-4 production by neutrophils." (PMID 36363785, 2022). "In the study, the results showed that the levels of pro-inflammatory cytokines (IL-2, IL-4, IL-6, TNF-α, and IFN-γ) were not different between mild, moderate, and severe/critical groups of children with COVID-19." (PMID 36294306, 2022). "We investigated the circulating levels of IFNγ, IL-4, sIL-4R, IL-5, IL-9, IL-17A, IL-17F, IL17-E/25, IL-22 and sCD30 in surviving and non-surviving severe COVID-19 patients and healthy controls." (PMID 36142255, 2022). "Conversely, significantly higher levels of GM-CSF, IFN-β, IL-10, and IL-2 and low levels of Eotaxin, IL-4, IL-5, MCP-1, and MIP-1β, were distinctive to Non-SOT COVID-19 patients relative to HCs, but not in SOTRs." (PMID 35075453, 2022). "While the levels of IP-10, IL-15 and IL-18 were exclusively increased in SOTRs with COVID-19, Non-SOT patients with COVID-19 showed solely higher levels of IFN-β, IL-2, IL-10, GM-CSF and low levels of Eotaxin, MCP-1, MIP-1β, IL-4, IL-5." (PMID 35075453, 2022). "In the acute COVID-19 group, younger patients had higher levels of TNF-α, and patients without comorbidities had higher levels of TNF-α, IL-4 and IL-2 (p<0.05)." (PMID 35846757, 2022). "Strikingly, IL-4, a Th2 cytokine, was absent in the lungs of pandemic influenza A(H1N1) patients but expressed in COVID-19 subjects." (PMID 33995342, 2021). "In contrast, the serum levels of IL-4, IL-6, IL-10, interferon-γ, and TNF-α were lowest in infected HD patients compared to non-infected HD patients or COVID-19-infected patients with normal renal function." (PMID 33466527, 2021). "Proinflammatory molecules, such as IL-2, IL-4, IL-5, IL-6, IL-10, IL-13, TNF-α, IFN-Υ, and CRP, were found at higher levels in COVID-19 patients with DM than in COVID-19 patients without DM." (PMID 34786431, 2021). "The presence of IL-4, greatly expressed in fatal SARS cases, was also not detected in the plasma of COVID-19 patients." (PMID 32916812, 2020).
COVID-19 (continued). "The production of cytokines in COVID-19 patients and CD4+ T lymphocytes isolated from SARS-CoV-2-vaccinated subjects stimulated with a peptide pool predominantly expressed IL-2 and IFN-γ, whereas IL-17A, IL-4, and IL-10 were less frequent and not significant." (PMID 38140191, 2023). "In addition to IL-6, the serum levels of IL-2R, IL-10, IL-1β, IL-4, IL-8, IL-17 and TNF-α were also elevated in both severe and non-surviving COVID-19 patients." (PMID 35237162, 2022). "Both studies uniformly describe stable cellular immune responses against SARS-CoV-2 including IFN-γ release as does our study but also of other cytokines (IL-2, IL-4, TNF-α etc.)and proliferation assays in SOT convalescents similar to non-IS-Con up to twelve months after COVID-19." (PMID 36322587, 2022). "Serum inflammatory factor levels of IL-2, IL-1β, IL-5, IL-4, IL-6, IL-8, IL-10, IL-17, IL-12P70, IFN-α, TNF-α, IFN-γ, endotoxin, CRP, and hs-CRP of non-severe COVID-19 patients across different age groups (< 50, 50–60, 60–70, and ≥ 70 years) were not significantly different." (PMID 33065551, 2020). "In addition, regardless of whether PD patients had COVID-19, the levels of TNF-α and IL-17 were greater in PD patients than in HCs, whereas the level of IL-4 was lower in PD patients than in HCs." (PMID 40292283, 2025). "Further, IL-4, IL-9, CCL5, CCL8, GM-CSF, and PDGF are exclusively induced by SARS-CoV-2 and these differences may explain why multi-organ injury including testicular damage and long-term sequelae is observed in COVID-19 patients and not with influenza virus." (PMID 37200377, 2023). "Moreover, the correlation coefficients for IL-4 and IL-2, IL-4 and TNF-α, and NK cells and T cells were the lowest in nonmetastatic patients, followed by metastatic and nonsevere COVID-19 patients, and were the highest in severe COVID-19 patients." (PMID 34712741, 2021).
allergic asthma (300 papers, 2004 to 2026). A asthma with a basis in a pathological type I hypersensitivity reaction. "Although TNF-α levels remained unchanged, Th2 cytokines associated with allergic asthma (i.e. IL-4, IL-5, and IL-13) were substantially reduced in BALF following ITIH4 administration (p < 0.05)." (PMID 40410722, 2025). "Both subsets are highly proinflammatory and express various inflammatory cytokines and mediators such as Il4, Il5, Il13, Tnfsf11, Areg, Tgfb1, Calca and Furin, all of which are implicated in promoting allergic asthma and other allergic diseases." (PMID 40089475, 2025). "Allergen-specific CD4+ Th2 lymphocytes and their associated cytokines (interleukin-4 [IL-4], IL-5, and IL-13) are hallmark features of allergic asthma." (PMID 40401951, 2025). "This process promotes T-cell proliferation, cytokine secretion (such as IL-4, IL-5, and IL-13), mucus production, and airway remodeling—all hallmark features of allergic asthma." (PMID 40724678, 2025). "Th2 cytokines—including IL-4, IL-5, and IL-13—are strongly linked to mucus production and airway inflammation, playing vital roles in the development and progression of allergic asthma." (PMID 39806495, 2025). "There are many risk factors that lead to IL-4 over-exposure in the neonatal phase and childhood, including allergic asthma, allergies to foods such as milk and eggs, bronchiolitis, and measles virus infection in the early stage." (PMID 38315435, 2024). "During the beginning of allergic asthma, contact with allergens causes T-helper type 2 (Th2) cell activation in the immune system, which produces inflammatory cytokines such as IL-4, -5, and -13." (PMID 36034804, 2022). "The levels of Th2-associated cytokines (IL-4, IL-5, and IL-13) increased in various allergic asthma models; MSC treatments generally restored the Th1/Th2 balance and reduced the cytokine levels, as we also observed." (PMID 35835804, 2022). "The majority of patients with allergic asthma suffer from a type 2 immune response, which is associated with Th2-mediated cytokines, including IL-4, IL-5, IL-9 and IL-13." (PMID 35744915, 2022). "These behavioral and neuroimmune changes in offspring occur in response to allergic asthma-associated elevations in inflammatory cytokines in the dams—namely, IL-4, IL-5, IL-6, and IL-17 —and closely mirror observations reported in clinical settings." (PMID 36009104, 2022). "Maternal serum in the MAA dams showed elevated levels of the T-helper type 2 allergic asthma-associated cytokines, including IL-4 (p = 0.019), IL-5 (p = 0.0004), and IL-13 (p = 0.003), confirming an allergic asthma response." (PMID 36009104, 2022). "As a proof of concept, mutations within BATF prevents the development of allergic asthma for Batf promotes the production of pro-allergic IL-4 by Tfh cells in mouse." (PMID 35812386, 2022). "Imuno TF influenced cellular signaling associated to allergic asthma once downregulated STAT6 expression as well as decreased IL-4, IL-5, and IL-13 in lung and serum." (PMID 36685604, 2022). "The hallmark Th2 immune response of allergic asthma characterized by increased secretion of IL-13 and IL-4 is directly associated with AHR, a fundamental aspect of disease symptoms and morbidity." (PMID 34924814, 2021). "The most important cytokines associated with allergic asthma are IL-4, IL-13 and IL-5, that are related to the activity of immune cells such as T cells, B cells producing specific IgE antibodies, eosinophils and mast cells." (PMID 34946286, 2021). "Comparison of DEGs from UNS and SEN mice confirmed that AMs express genes associated with the M2 phenotype in allergic asthma 24, likely because the allergic lung environment is enriched in IL-4 and IL-13, which drive M2 polarisation." (PMID 34764248, 2021). "Elevated IgE levels in the serum is a hallmark feature of allergic asthma, where T2-cytokines IL-4 and IL-13 promote B cell differentiation, isotype class switching and IgE secretion." (PMID 34777398, 2021).